SRP9 (signal recognition particle 9)
Description:
Component of the signal recognition particle (SRP) complex, a ribonucleoprotein complex that mediates the cotranslational targeting of secretory and membrane proteins to the endoplasmic reticulum (ER) (By similarity). SRP9 together with SRP14 and the Alu portion of the SRP RNA, constitutes the elongation arrest domain of SRP. The complex of SRP9 and SRP14 is required for SRP RNA binding (By similarity).
Synonyms: ALURBP
Tractability: Small molecule: a structure with a bound ligand is known. PROTAC: ubiquitination databases record sites on it; its protein half-life has been measured.
Gene: Protein-coding gene on chromosome 1 (225,777,699 to 225,790,670, forward strand). Ensembl gene ENSG00000143742.
Subcellular location: Cytoplasm
Pathways (Reactome):
Metabolism of proteins: SRP-dependent cotranslational protein targeting to membrane
Gene Ontology:
Molecular function: protein binding; RNA binding; signal recognition particle binding; 7S RNA binding
Biological process: SRP-dependent cotranslational protein targeting to membrane; SRP-dependent cotranslational protein targeting to membrane, signal sequence recognition; negative regulation of translational elongation
Cellular component: cytosol; signal recognition particle receptor complex; signal recognition particle, endoplasmic reticulum targeting; cytoplasm; signal recognition particle
Genetic constraint (gnomAD): Loss-of-function variants: 1 observed, 7.6 expected, observed/expected ratio (o/e) 0.13, 90% interval 0.046 to 0.62. That is too few expected variants to judge how well the gene tolerates losing a copy. Missense variants: 27 observed, 60.81 expected, observed/expected ratio (o/e) 0.44, 90% interval 0.33 to 0.61. Synonymous variants: 14 observed, 21.44 expected, observed/expected ratio (o/e) 0.65, 90% interval 0.43 to 1.02.
Homologues: Orthologues: chimpanzee SRP9 (100% identical), guinea pig SRP9 (94% identical), mouse Srp9 (93% identical), pig SRP9 (92% identical), rabbit SRP9 (92% identical), rat Srp9 (91% identical), zebrafish srp9 (78% identical), tropical clawed frog srp9 (65% identical), macaque SRP9 (60% identical), dog SRP9 (56% identical), Caenorhabditis elegans ZK512.4 (45% identical), Drosophila melanogaster Srp9 (36% identical).
Diseases named in the same sentence as SRP9 in open-access papers:
SRP9 is named in the same sentence as 19 diseases in open-access papers, as found by Europe PMC text mining. Sharing a sentence is not in itself a finding about the gene and the disease. The quoted sentences say what the papers report.
colorectal cancer (7 papers, 2013 to 2022). A primary or metastatic malignant neoplasm that affects the colon or rectum. "Colorectal cancer upregulates adenosine-to-inosine RNA editing enzymes which edit the mRNA of SRP9 causing upregulation and indicating SRP9 can be used as a prognostic marker in these cancers." (PMID 35754847, 2022). "More importantly, proteomic analysis of CRC tissues and validation of clinical specimens suggested that SRP9 acted as a potential biomarker for colorectal cancer." (PMID 35590292, 2022). "Gucy2c and Srp9 have been shown to be overexpressed in colorectal cancer cells and were recently shown to function as a candidate biomarker for colon cancer." (PMID 23555558, 2013). "Previous study has shown that the increased expression of SRP9 in colorectal cancer is highly likely to play a promoting cancer role, but its function, regulatory mechanism, and effect on tumor cells remain unclear." (PMID 35590292, 2022). "The proteomic expression analysis of human colorectal cancer showed the upregulation of SRP9 with hypoxic adaptation of the tumor microenvironment of heterogeneous primary human tumor tissues, suggesting the role of SRP9 in RAPP in cancer." (PMID 36338771, 2022). "In addition, SRP9 has shown potential as a prognostic marker for colorectal cancer and non-Hodgkin’s lymphoma." (PMID 36518216, 2022). "Furthermore, SRP9 also showed higher expression levels in human colorectal cancer." (PMID 28286461, 2017). "In our study, we sufficiently proved that the expression of SRP9 was upregulated in CRC, which was consistent with a previous report detected in surgical human colorectal cancer tissues." (PMID 35590292, 2022). "Moreover, SRP9 might be a potential biomarker for colorectal cancer." (PMID 35590292, 2022).
breast carcinoma (5 papers, 2020 to 2022). "It has been indicated that in breast cancer, deficiencies of SRP9 and SRP14 activate RIG-1, which further causes an interferon response, increases inflammation, and leads to breast cancer metastasis." (PMID 36518216, 2022). "For instance, in breast cancer, SRP9/14 functions as an RNA binding protein to bind RN7SL1, shielding the virus-like inflammatory response." (PMID 35590292, 2022). "Collectively, signaling protein analysis revealed a highly activated pathway of post-translational modification and protein transport to the rough endoplasmic reticulum (via GFM, MRPS12, RPS21, and SRP9), suggested circuitry to predict breast cancer outcomes." (PMID 32252260, 2020).
colon cancer (3 papers, 2013 to 2022). "We investigated the differences in the expression of DAB2IP, HSP90AA1 and SRP9 among different subtypes of CMS classification in colon cancer." (PMID 35590292, 2022). "Regulation of the expression of SRP genes and proteins in liver and colon cancer remains to be elucidated; however, alterations in the expression levels of SRP9/14 and SRP19 indicate a key role for SRP in gastro-related cancer." (PMID 34113652, 2021). "SRP9 mRNA was found up-regulated in hepatocellular carcinoma via gene array studies while a proteomic analysis has shown it was overexpressed in patients with colorectal adenocarcinoma, suggesting SRP9 as a candidate biomarker for colon cancers." (PMID 34113652, 2021). "Colon cancer-related genes such as Nek11, Gucy2c, Srp9, Tle6, and Pdgfrl were also overrepresented in the time-course clusters identified by the MNI analysis in the epididymal and subcutaneous fat tissues and gastrocnemius muscle of mice with diet-induced obesity." (PMID 23555558, 2013).
Alzheimer disease (1 paper, 2022). A progressive, neurodegenerative disease characterized by loss of function and death of nerve cells in several areas of the brain leading to loss of cognitive function such as memory and language. "SRP9 has also been shown to be associated with plaque formation in Alzheimer’s disease, suggesting there could be a causal link between BC200, SRP9, and the pathogenesis of Alzheimer’s disease." (PMID 35754847, 2022).
asthma (1 paper, 2018). "In previous studies, the −28C/G allele of the CCL5 promoter region was uniquely associated with nonallergic asthma in the Japanese population, and a cluster research found that the polymorphism in SRP9 (rs4653433) was related to nonallergic asthma." (PMID 29751569, 2018).
hepatocellular carcinoma (1 paper, 2021). A malignant tumor that arises from hepatocytes. "The heterodimer SRP9/14 levels increased in the serum of the H22 hepatoma-bearing mice and its expression reduced by the antitumoral Scutellaria barbata polisaccharides." (PMID 34113652, 2021).
liver cancer (1 paper, 2022). An epithelial or non-epithelial malignant neoplasm that arises from the liver. "In addition, SRP9 expression is upregulated in liver cancer." (PMID 35590292, 2022).
pulmonary hypertension (1 paper, 2022). Increased pressure within the pulmonary circulation due to lung or heart disorder. "To further investigate the relationships among the SRP-DGs and risk of SSc-PH, we constructed a nomogram model using seven SRP-DGs (RPL32, RPS12, RPS14, RPS23, RPS3, RPS7, and SRP9) to predict the risk of pulmonary hypertension complications in patients with SSc." (PMID 36518216, 2022).
cancer (9 papers, 2013 to 2022). A tumor composed of atypical neoplastic, often pleomorphic cells that invade other tissues. "Among the seven SRP-DGs, downregulation of SRP9 is related to the development and progression of multiple types of cancer." (PMID 36518216, 2022). "Studies on the Alu-domain associated with SRP9 and SRP14 indicated that they are involved in several human cancers and can be used as diagnostic markers." (PMID 36338771, 2022). "SRP subunits could be predictive markers of cancer, though only SRP9 and SRP14 have been investigated as prognostic tools." (PMID 35754847, 2022). "Furthermore, targeting the noncanonical role of SRP9/14 in SGs formation and disassembly could be a potential therapeutic strategy for the treatment of many human diseases where SGs are mainly involved, such as pathogenesis of neurodegenerative diseases, viral infection, aging and cancers." (PMID 34113652, 2021).
tumor (3 papers, 2012 to 2022). "SRP9 sequencing chromatogram traces showed an adenine (in tumor DNA) and a guanine (in tumor RNA) substitution which might be attributed to ADAR, in fact ADAR carries out adenosine to inosine editions and inosine is read as guanosine by sequencing instruments." (PMID 23137041, 2012). "Recently, in a study carried out at both genomic and transcriptional levels, SRP9 and COG3 mRNA expressed in tumor cells were clearly shown to carry SBS that were conflicting with the genome sequence." (PMID 23137041, 2012).
neurological diseases (1 paper, 2022). "Srp9 impairs the expression of α-amino-3-hydroxy-5-methyl-4-isoxazole propionic acid (AMPA) and N-methyl-D-aspartate (NMDA) receptors in hippocampal neurons, which is involved in neurological diseases, such as seizures." (PMID 36614117, 2022).
SRP9 also shares sentences with these, for which no sentence is quoted: autism (1 paper); colorectal adenocarcinoma (1); epilepsy (1); neurodegenerative disease (1); neuroferritinopathy (1); non-Hodgkin lymphoma (1); Obesity (1); ZTTK syndrome (1).